NLRP3 (NLR family pyrin domain containing 3)
Diseases named in the same sentence as NLRP3 in open-access papers (continued):
Sharing a sentence is not in itself a finding about the gene and the disease.
glaucoma (continued). "Previous studies have reported ocular involvement in NLRP3-AID, including conjunctivitis, papilledema, optic atrophy, keratitis, uveitis, cataract and glaucoma." (PMID 37480029, 2023). "Patients with NLRP3-AID have been reported to present with conjunctivitis, uveitis, papilledema, optic atrophy, cataract and glaucoma." (PMID 37480029, 2023). "Apart from the NLRP3 inflammasome, studies have shown that NLRC4 is also involved in RGC pyroptosis in an acute glaucoma mouse model, but the precise mechanism requires further investigation." (PMID 35836195, 2022). "The NLRP3 inflammasome can also link hypoxia to inflammation and suggests how hypoxia, and thus increased IOP in glaucoma, can contribute to inflammation." (PMID 34366851, 2021). "In particular, the NLRP3 inflammasome pathway in glial cells of the ONH and retina appears to play a critical role in axon degeneration and death of RGCs in glaucoma." (PMID 34439904, 2021). "Inhibition of HMGB1 resulted in reduced NLRP3 and IL-1B levels, which also reduced RGC death and glaucoma severity." (PMID 34439904, 2021). "TGF-β is involved in damage to the ONH in glaucoma and TGF-β can induce activation of the NLRP3 inflammasome, which has also been demonstrated to be involved in fibrosis." (PMID 34439904, 2021). "Taken together, these data suggested that either direct knockout of TXNIP or blockade of the NLRP3 pathway, which is essential for the effect of TXNIP, could exert a neuroprotective effect in experimental glaucoma." (PMID 39736512, 2024). "Moreover, GSK872 and Nec-1 can protect RGCs from necroptosis and suppress NLRP3 inflammasome activation through inhibition of RIP1/RIP3/MLKL pathway, conferring a novel neuroprotective treatment for glaucoma." (PMID 36289519, 2022). "However, in the more clinically relevant microbead-induced mouse model of glaucoma, where IOP was elevated, treatment with a commercially available NLRP3-specific inhibitor (MCC950) was also shown to prevent axon degeneration and death of RGCs." (PMID 34439904, 2021). "Additionally, key mediators of the Toll-like receptor pathway, inflammasome pathway, and complement cascade that have been identified in human and experimental glaucoma were also examined, specifically TLR4, NLRP3, and complement components C3 and C1Q." (PMID 31570110, 2019). "In glaucoma, the ON glial cells become activated, which in turn damage the axons leaving the eye and further trigger inflammatory cell recruitment to the injury sites; ONH astrocytes constitutively express NLRP3 and injury to the ONH may also activate the NLRP3 inflammasome pathway in these cells." (PMID 34439904, 2021).
migraine (27 papers, 2019 to 2025). "NLRP3 inflammasome is also involved in the cortical neuroinflammation and neurodegenerative changes associated with trigeminal neuralgia and migraine." (PMID 36361825, 2022). "Activation of nucleotide-binding domain (NOD)-like receptor family pyrin domain containing 3 (NLRP3) inflammasome by mitochondrial reactive oxygen species can cause hyperalgesia, which is involved in migraine pathophysiology." (PMID 35959386, 2022). "Our study demonstrates that the expression of the NLRP3 inflammasome was upregulated in the migraine-associated pain mouse model that was induced by recurrent NTG stimulation." (PMID 30971286, 2019). "To further confirm the role of NLRP3 activation in migraine-associated pain, we tested the effects of the NLRP3 inhibitor MCC950 on the mice with repeated NTG stimulation." (PMID 30971286, 2019). "Although the treatment approaches for migraine are not yet well established, IL-1 receptor antagonists suppress migraine attacks in patients with the cryopyrin-associated periodic syndrome, where mutations in the inflammasome component NLRP3 result in over secretion of IL-1β." (PMID 37176049, 2023). "Through the induction of NTG (10 mg/kg) injection, researchers have observed that the end products of the NLRP3 inflammasome, specifically cytokines, elevate neurotrophic factors that play a crucial role in the pathological processes associated with the progression of migraines." (PMID 38836002, 2024). "Notably, the conditions for NLRP3 activation, such as the high concentrations of extracellular K+ ions, increased peroxynitrite, mitochondrial dysfunction and the generation of reactive oxygen species (ROS), usually underlie the generation of a migraine." (PMID 30971286, 2019). "The NLRP3 inflammasome plausibly constitutes a target for the control of CM-associated pain, and its inhibition may represent a new therapeutic rationale and approach for migraine treatment." (PMID 30971286, 2019). "Together, these data indicate the IL-1/NLRP3 axis as a testable therapeutic node in the comorbid migraine and TMDs." (PMID 41465107, 2025). "The involvement of P2 × 7R in the headache process has already been reported, as P2 × 7R is involved in the migraine process by activating NLRP3 and thus releasing IL-1β during migraine development." (PMID 38573415, 2024). "The roles of NLRP3 and MMP9 in migraine pathophysiology not only sheds light on the underlying mechanisms of the disease but also identifies potential therapeutic targets." (PMID 38836002, 2024). "One of the main targets of the BHB is the NLRP3 inflammasome, a multiprotein complex activated in the central nervous system at the onset of migraine attacks." (PMID 39770945, 2024). "These receptors can be potential targets for impeding the generation of proinflammatory molecules via NLRP3 inflammasomes in the brain, potentially aiding in the treatment of migraines." (PMID 38836002, 2024). "They reveal that NTG, especially at 10 mg/kg, consistently induces migraine-like symptoms in rodents by activating NLRP3 inflammasome and stimulating proinflammatory molecule production." (PMID 38836002, 2024). "Several key discoveries from this systematic review were emphasized, notably the association between PX7R, RIPK, P2X4 receptor activation, NLRP3, and MMP9 in the genesis of migraines." (PMID 38836002, 2024). "This study delves into the potential roles of NLRP3 and MMP9 as biomarkers in the pathophysiology of migraine, shedding light on the underlying mechanisms of this complex neurological disorder." (PMID 38836002, 2024). "The systematic review reveals a significant association between NLRP3 and MMP9 expression levels and migraine progression." (PMID 38836002, 2024). "Nowadays, researchers are especially targeting NLRP3 inflammasomes which has a robust connection to migraine and predicting MMP9 additionally playing a major role in the migraine attack." (PMID 38836002, 2024).
migraine (continued). "Studies investigate a range of molecular targets implicated in migraine pathogenesis, such as CGRP, NLRP3 inflammasome, and PACAP/PAC1R signaling." (PMID 38836002, 2024). "Given the upregulation of P2X7R and activation of its downstream NLRP3 inflammasome signaling pathway in the IS-induced migraine mice model, inhibition of P2X7R with BBG (a specific P2X7R antagonist) is a potential effective therapeutic approach." (PMID 35780081, 2022). "The present study was the first to demonstrate that NLRP3 inflammasome-mediating pyroptosis occurs in cerebral cortex and hippocampus of a mouse model of IS-induced migraine." (PMID 35780081, 2022). "Here in this review, we provide an up-to-date review of the recent findings of NLRP3 inflammasome in chronic pain conditions, including inflammatory pain, neuropathic pain, migraine, bone cancer pain, and morphine-induced analgesic tolerance and hyperalgesia." (PMID 33785039, 2021). "Nucleotide-binding domain (NOD)-like receptor family pyrin domain containing 3 (NLRP3) is the best characterized inflammasome and there is emerging evidence of its role in a variety of inflammatory pain conditions, including migraine." (PMID 34112082, 2021). "VNS shows that cholinergic anti-inflammatory pathway is important in migraine pathophysiology via reduction of CSD susceptibility, inhibition of mtDNA release, and the NLRP3 inflammasome." (PMID 34112082, 2021). "The therapeutic potential of compounds targeting NLRP3 inflammasome signaling pathways in migraine, although promising, remains to be assessed." (PMID 34112082, 2021). "A possible link between mitochondrial dysfunction and neuroinflammation is the demonstration of NLRP3 inflammosome activation by mitochondrial reactive oxygen species which was postulated to participate in several CNS disorders including migraine." (PMID 34615455, 2021). "These approaches have revealed a key contribution of NLRP3 to migraine, with MCC950, a specific NLRP3 antagonist, reducing periorbital and hind paw mechanical hypersensitivity and reversing increased expression of IL-1β in trigeminal ganglia." (PMID 32973552, 2020). "In addition, upstream inhibition of the NLRP3 inflammasome reduces NTG-induced hyperalgesia in preclinical migraine models." (PMID 41465107, 2025). "Both IL-1β and NLRP3 play crucial roles in the pathogenesis of migraine." (PMID 41441603, 2025). "Furthermore, the review highlights the inflammatory cascade initiated by NLRP3 activation and subsequent MMP9 release as a potential mechanism underlying migraine pathogenesis." (PMID 38836002, 2024). "NLRP3 inflammasome activation and MMP9-mediated neuroinflammation may modulate the susceptibility to CSD, influencing the frequency and severity of migraine attacks." (PMID 38836002, 2024). "A potential new approach to treating migraines could be to inhibit NLRP3, which would lessen hyperalgesia and central sensitization." (PMID 38836002, 2024). "Additionally, the NLRP3 inflammasome is upregulated in trigeminal ganglion neurons relevant to migraine pain." (PMID 38202145, 2023). "Another study demonstrated that the expression of the NLRP3 inflammasome was upregulated in a migraine-relevant pain mouse model (that is pain was induced by recurrent NTG stimulation), shown by an increase in NLRP3 expression that was associated with IL-1β activation." (PMID 34112082, 2021). "BoNT/A may have a therapeutic function in migraines by reducing the expression of NLRP3 and IL-1β." (PMID 38836002, 2024). "Consequently, the microglial P2X7R/NLRP3 inflammasome may be a prospective therapeutic target for treatment of MOH resulting from the repeated use of acute analgesics for migraine." (PMID 37377770, 2023). "Thus, inhibition of NLRP3 inflammasome may represent a potential therapeutic approach for alleviating migraine." (PMID 33785039, 2021). "However, few studies have investigated the relationship of NLRP3 with migraines." (PMID 30971286, 2019).
migraine (continued). "Elevated levels of both NLRP3 and MMP9 are consistently observed in migraine patients compared to controls, suggesting their potential involvement in the pathophysiology of the condition." (PMID 38836002, 2024). "This systematic study is motivated by the exploration of the roles of NLRP3 and MMP9 in the onset of migraine attacks." (PMID 38836002, 2024). "This review summarizes 22 preclinical studies on Nitroglycerin (NTG), NLRP3, MMP9, and related biomarkers in migraine." (PMID 38836002, 2024). "This study seeks to investigate the potential connection between NLRP3 and MMP9 in migraine pathology." (PMID 38836002, 2024). "It highlights the interconnected relationships between NLRP3, MMP9, and various other biomarkers, providing a comprehensive overview of their potential contributions to migraine attacks." (PMID 38836002, 2024). "Activation of NLRP3 and upregulation of MMP9 contribute to neuroinflammation, which is increasingly recognized as a key factor in migraine pathogenesis." (PMID 38836002, 2024). "Pharmacological blocking NLRP3 or IL-1β with the NLRP3 antagonist MCC950 or IL-1ra not only improved NTG-induced hyperalgesia, but also inhibited the biomarkers related to central sensitization of migraine in TNC, such as p-ERK, c-Fos, and CGRP." (PMID 33785039, 2021). "We evaluated the expression levels of NLRP3 and its downstream interleukin (IL)-1β protein in the trigeminal nucleus caudalis (TNC; which is a central area relevant to migraine pain) at different time points." (PMID 30971286, 2019). "Therefore, in the NTG-induced migraine-associated pain model, PN may be produced by NTG-derived NO; activate the NLRP3 molecular platform in microglia, leading to the release of downstream inflammatory mediators; and participate in the formation of central sensitization." (PMID 30971286, 2019). "This hypothesis sets the stage for establishing a robust connection between NLRP3 and MMP9 in the context of migraines." (PMID 38836002, 2024). "From a clinical perspective, there is a need for increased research emphasis on NLRP3 and BDNF, as this may offer more effective solutions for migraine treatment." (PMID 38836002, 2024). "After extensive literature reviews and discussions, we concluded that the NTG-inducing model (10 mg/kg) is the most suitable for inducing the production of NLRP3, MMP9, and other proinflammatory molecules in rodents, making it widely accepted as a universal animal model for studying migraines." (PMID 38836002, 2024). "Furthermore, the authors found that NLRP3 and IL-1β expression was significantly upregulated in the microglia of trigeminal nucleus caudalis (TNC), a place that receives and integrates pain signals from the trigeminal area and is considered as a central area relevant for migraine." (PMID 33785039, 2021).
hearing loss (26 papers, 2016 to 2026). "Gain-of-function mutations of NLRP3 are known to cause syndromic hearing loss in systemic autoinflammatory diseases- CAPS and autosomal dominant non-syndromic hearing loss locus (DFNA43) in patients." (PMID 39277762, 2024). "In contrast, a significant cohort of CAPS patients with NLRP3 mutated in the NACHT domain reported 42% of patients with hearing loss and 97% of patients with skin involvement." (PMID 39195255, 2024). "Atypical forms of CAPS were particularly prevalent in patients with the K829T, Y859C, Y859H, and R918Q variants of NLRP3, with 94.1% (32/34) of hearing loss and only 30.7% (8/26) of skin manifestations." (PMID 39195255, 2024). "Recently, it has been shown that NLR family pyrin domain containing 3 (NLRP3) inflammasome activation in VS is correlated with VS-induced hearing loss." (PMID 37627117, 2023). "The p.Arg918Gln mutation in NLRP3 can cause non-syndromic sensorineural hearing loss as well as an atypical presentation of CAPS." (PMID 32194497, 2020). "Additionally, it has been observed that nucleotide-binding oligomerisation domain-, leucine-rich repeat-, and pyrin domain-containing protein 3 (NLRP3)-inflammasome is involved in the development of kanamycin-related hearing loss." (PMID 40512245, 2025). "Targeting NLRP3 may ultimately redefine treatment paradigms for preventing or halting progressive hearing loss." (PMID 41046290, 2025). "D305N mutation was one of the most frequent NLRP3 mutations and suggested it may be associated with early disease onset, a chronic course, and hearing impairment." (PMID 38481988, 2024). "There is data emerging that the NLRP3 inflammasome may be linked to hearing loss in a number of conditions including genetic hearing loss and vestibular schwannoma associated hearing loss." (PMID 39277762, 2024). "Therefore, patients harboring NLRP3 variants in the LRR domain tend to exhibit a higher incidence of hearing loss and lower prevalence of skin involvement compared to those with variants in the NACHT domain." (PMID 39195255, 2024). "In addition, we further discuss the interplays linking ROS generation, NLRP3 inflammasome activation, and autophagy underlying the pathogenesis of deafness, including ototoxic drugs-, noise- and aging-related hearing loss." (PMID 36891515, 2023). "In contrast, sensorineural hearing loss was reported for 79% of patients with NLRP3 pathogenic variants and 18% with NLRP3 low-penetrance variants, indicating that mutations of high-penetrance may be more pathogenic for hearing loss." (PMID 38343435, 2023). "In contrast, the second family experienced hearing loss in the first 10 years which was accompanied by autoinflammatory signs and symptoms, including oral ulcers, without serologic signs of inflammation, contributing to an atypical NLRP3-AID phenotype." (PMID 34671876, 2022). "Future investigations into the role of NLRP3 in the cochlea and the pathogenesis of hearing loss may shed light on the etiology of other sensorineural hearing loss cases." (PMID 35572943, 2022). "Based on these findings, we concluded that local cochlear activation of the NLRP3 inflammasome could induce cochlear autoinflammation and sensorineural hearing loss." (PMID 35572943, 2022). "Cochlear implantation could work as a rescue measure in cases of advanced, profound NLRP3-related hearing loss, and an anti-IL-1β agent could be beneficial for early diagnosed, mild hearing loss." (PMID 35812087, 2022). "DFNA34 is an autosomal dominant non-syndromic sensorineural hearing loss caused by NLRP3 variants." (PMID 35572943, 2022). "Recently, hearing loss (HL) has been found to be the sole or major manifestation of NLRP3-AID." (PMID 35720340, 2022). "We review syndromic and non-syndromic hearing loss phenotypes caused by an NLRP3 mutation." (PMID 32194497, 2020).
hearing loss (continued). "This overexpression is potentially associated with hearing loss, and this model could also provide a valuable tool to investigate the link between mutant Nlrp3 overexpression and hearing loss, further revealing the underlying mechanism of inflammasome activation-mediated hearing loss." (PMID 35812087, 2022). "Previous studies have shown that cisplatin can trigger the assembly of the NLRP3 inflammasome and activate downstream pathways; thus, we speculated that the NLRP3 inflammasome may also have a vital effect on the pathogenesis of cisplatin-induced hearing loss." (PMID 35529876, 2022). "It is reported that the elevated NLRP3 inflammasome, cytokines, and reactive oxygen species could activate macrophages or autophagy pathways, disrupt the endothelial cell integrity of the stria vascularis and increase hair cell apoptosis, and contribute to hearing loss." (PMID 37383219, 2023). "Whereas, minority NLRP3 mutations in other regions (e.g., LRR domain) are related to syndromic and non-syndromic hearing loss, such as deafness autosomal dominant 34 (DFN34) and keratitis fugax hereditaria (KFH) diseases." (PMID 36891515, 2023). "Gain-of-function mutations in the NLRP3 gene are frequently associated with both syndromic and nonsyndromic hearing loss, and animal models expressing these mutations replicate cochlear inflammation and hearing deficits, validating their pathogenic role." (PMID 41046290, 2025). "Mutations in the NLRP3 gene are responsible for autosomal dominant autoinflammatory disease (NLRP3-AID), and hearing loss (HL) may be the primary or even the only significant symptom of NLRP3-AID." (PMID 40299348, 2025). "However, the symptoms observed in these families were varied; one family reported hearing loss with an age of onset in the second to fourth decade of life, with no additional physical signs or symptoms of NLRP3-AID." (PMID 34671876, 2022). "Taken together, our results suggest that NLRP3 inflammasome activation may mediate cisplatin-induced MC pyroptosis in cochlear stria vascularis, and TXNIP is a possible upstream regulator, which may be a promising therapeutic target for alleviating cisplatin-induced hearing loss." (PMID 35529876, 2022). "Sanger sequencing in all 10 family members revealed a p.E313K (NM_001127462: c.G937A) mutation in NLRP3, a gene not included in any of the targeted NGS panels for deafness in previous reports (see Section 4 for details), as the only pathogenic mutation segregating with the hearing loss phenotype." (PMID 27965898, 2016).